CLDN2 (claudin 2)
Diseases named in the same sentence as CLDN2 in open-access papers (continued):
Sharing a sentence is not in itself a finding about the gene and the disease.
Barrett esophagus (4 papers, 2017 to 2023). Esophageal lesion lined with columnar metaplastic epithelium which is flat or villiform. "The association of Claudin 2 high expression with clinicopathologic features in esophageal adenocarcinoma was analyzed." (PMID 28212604, 2017). "In addition, the authors indicated that gastroesophageal reflux disease may induce the overexpression of CLDN2 and increase the risk of the development of Barrett’s oesophagus." (PMID 38201579, 2023). "Claudin-2, on the other hand, had significantly increased expression in esophageal adenocarcinoma compared with its expression in Barrett’s esophagus." (PMID 37627123, 2023). "The presented study provides new insights into the role of TJ proteins such as CLDN2 in the pathogenesis of Barrett’s oesophagus and oesophageal cancer." (PMID 38201579, 2023). "Abu-Farsakh and co-workers showed that claudin-2 is highly expressed in esophageal adenocarcinoma and its premalignant precursors." (PMID 37627123, 2023). "Log-rank test was used to compare the effect of Claudin-2 expression in survival rates for patients with esophageal adenocarcinoma." (PMID 28212604, 2017). "Claudin-2 expression increases intracellular permeability, promoting cellular changes which could lead to metaplasia and Barrett’s esophagus." (PMID 37627123, 2023). "Moreover, the expression of CLDN3 and CLDN4 was significantly elevated both in Barrett’s oesophagus and OAC in comparison to the foveolar epithelium, while in OAC, the expression of CLDN2 was significantly higher in comparison to that in Barrett’s oesophagus." (PMID 38201579, 2023). "Claudin-2 expression was examined by immunohistochemistry on tissue microarrays, containing EAC, high grade dysplasia (HGD), low grade dysplasia (LGD), Barrett’s esophagus (BE), columnar cell metaplasia (CM), squamous cell carcinoma (SCC), and squamous epithelium (SE) cases." (PMID 28212604, 2017).
colon adenocarcinoma (4 papers, 2021 to 2023). "Upregulation of CLDN2 by TNFα was further confirmed in a human colonic adenocarcinoma cell line (Caco2) treated with TNFα (20 ng/mL) or IL-1β (10 ng/mL), respectively." (PMID 37287024, 2023).
cystitis (4 papers, 2017 to 2021). Inflammation of the urinary bladder. "Here, we examined the mechanisms underlying organ hyperactivity and pain in a model of cystitis caused by adenoviral-mediated expression of claudin-2 (Cldn2), a tight junction protein that forms paracellular pores and increases urothelial permeability." (PMID 30940909, 2019). "We posit that this discrepancy reflects differences in the underlying mechanisms that lead to cystitis in rats treated with cyclophosphamide and those overexpressing Cldn2." (PMID 28560313, 2017). "Together, our studies indicate that the model of cystitis induced by the overexpression of Cldn2 in the urothelium resembles the symptoms and histologic features of human IC/BPS, particularly the bladder-derived pelvic pain." (PMID 28560313, 2017). "Conversely, claudin-2 (Cldn2) is a tight junction-associated protein, which has been found to be upregulated in bladder biopsies from patients with IC/BPS, as well as in rodent models for cystitis." (PMID 34943535, 2021).
food allergy (4 papers, 2013 to 2021). Gastrointestinal disturbances, skin eruptions, or shock due to allergic reactions to allergens in food. "In fact, the strong Th2 adjuvant cholera toxin (CT), commonly used to induce food allergy in mouse models, enhances the expression of Cldn2, Muc2, Il17, and Il6 in the small intestine when administered with food proteins to produce sensitization." (PMID 34684302, 2021). "In this study, the expression of Cldn2 in the epithelial layer of mice and patients with food allergy was observed by immunohistochemistry." (PMID 23990874, 2013). "We observed that strong Cldn2 expression in the intestine of mice with intestinal antigen-specific hypersensitivity and in patients with food allergy." (PMID 23990874, 2013). "The results showed that exposure to SEB or CT promoted the expression of Cldn2 in the intestinal epithelial cells; Cldn2 facilitated absorption of protein antigens; blocking Cldn2 prevented the development of food allergy in a murine model." (PMID 23990874, 2013). "In addition, CLDN2 is the main pore-forming protein and its expression is strongly upregulated in the duodenal biopsies of patients with food allergy." (PMID 31810340, 2019). "Finally we observed the expression of Cldn2 in the human intestinal epithelium of patients with food allergy." (PMID 23990874, 2013). "The results showed that the positive immune staining of Cldn2 was observed in the epithelial layer of the small intestine that was weakly stained in naïve control mice, and strongly stained in sensitized mice as well as patients with food allergy." (PMID 23990874, 2013). "The results imply that Cldn2 may be an important factor in the food allergy related intestinal hypersensitivity." (PMID 23990874, 2013). "As shown by confocal microscopy, the weak staining of Cldn2 was detected in the specimens from non-food allergy patients while the strong positive staining was observed in the specimens from patients with food allergy." (PMID 23990874, 2013).
kidney stones (4 papers, 2024 to 2025). "Like claudin-2–KO mice, kidney stone formers with idiopathic hypercalciuria have a defect in PT calcium reabsorption." (PMID 41066193, 2025). "At Xq22.3, we assigned CLDN2 for its known role in nephrolithiasis development and a knock-out mouse model that showed kidney stone formation." (PMID 38233393, 2024). "The clinical significance of this is uncertain, however, as we found no sex difference in the association of CLDN2 common variants with kidney stones in our previous genome-wide association study." (PMID 41066193, 2025). "In this study, CLDN1 expression was found to be increased in patients with a history of recurrent kidney stones and to be highly positively correlated with CLDN4, CLDN7 and CLDN14 and moderately correlated with CLDN2 and CLDN8." (PMID 39345805, 2024).
lymph node metastasis (4 papers, 2013 to 2025). "High CLDN2 expression correlates with lymph node metastasis and advanced stage." (PMID 40687428, 2025). "However, the association between claudin-2 protein expression with high clinical stage and lymph node metastasis has not been observed." (PMID 23919729, 2013).
osteosarcoma (4 papers, 2018 to 2022). A usually aggressive malignant bone-forming mesenchymal neoplasm, predominantly affecting adolescents and young adults. "Another study suggested that in osteosarcoma cells claudin-2 loss augmented migration via the afadin/ERK pathway." (PMID 31726679, 2019). "Osteosarcoma tissue exhibits reduced levels of CLDN2 expression, thereby inhibiting the Ras/Raf/MEK/ERK signaling pathway via afadin and eventually reducing the capacity of osteosarcoma cells to migrate." (PMID 36620607, 2022). "Osteosarcoma cells have lower claudin-2 expression than normal osteoblasts, and this is associated with enhanced migration." (PMID 31726679, 2019). "In an earlier study, we investigated the expression of tight junction protein claudins (CLDNs) in human osteosarcoma (OS) cells, and the CLDN2 was found to be down-regulated in primary tumor cells compared with normal osteoblast cells." (PMID 30349422, 2018). "The complex and context-dependent action of the Claudin-2/Afadin axis is reinforced by a recent study that describes the reactivation of ERK signaling pathway via the down-regulation of Afadin by Claudin-2, which decreases the migratory potential of osteosarcoma (OS) cells." (PMID 30692208, 2019).
acute pancreatitis (3 papers, 2016 to 2024). An acute inflammatory process that leads to necrosis of the pancreatic parenchyma. "In this regard, a genome wide association study (GWAS) on pancreatitis identified polymorphisms at X-linked CLDN2 locus being robustly associated with recurrent acute pancreatitis and predominantly alcohol-related chronic pancreatitis in North American patients of European ancestry." (PMID 26820620, 2016). "While the role of genetics in predisposition to acute recurrent and/or chronic pancreatitis of different etiologies has been the focus of many studies (PRSS1, PRSS2, SPINK1, CFTR, CLDN2, CAP1), ASNase-related acute pancreatitis have only started emerging recently." (PMID 35582721, 2019).
Chronic colitis (3 papers, 2021 to 2023). A chronic inflammatory disease of the large intestine (colon, cecum and rectum). "The trend of Claudin-2 expression might explain how H. pylori exerts its aggravating effect in DSS-induced chronic colitis." (PMID 35331316, 2022). "Intriguingly, CagA−H.pylori was not responsible for upregulated claudin-2 compared to chronic colitis mice subgroup without H. pylori infection." (PMID 35331316, 2022). "pylori infection increases Claudin-2 expression and aggravates DSS-induced chronic colitis." (PMID 35331316, 2022).
chronic pancreatitis (3 papers, 2016 to 2022). A chronic inflammatory process causing damage and fibrosis of the pancreatic parenchyma. "In a genome-wide study, a CLDN2 risk allele, which is associated with an abnormal expression of CLDN2 protein in pancreatic acinar cells, was identified as a risk factor that interacted with alcohol consumption to accelerate the progression of chronic pancreatitis." (PMID 35052788, 2022). "A recent genome-wide association study (GWAS) identified association with variants in X-linked CLDN2 and MORC4, and PRSS1-PRSS2 loci with chronic pancreatitis (CP) in North American patients of European ancestry." (PMID 26820620, 2016).
colorectal tumour (3 papers, 2021 to 2023). "It was demonstrated that the aberrant expression of CLDN2, CLDN4, CLDN5, CLDN7, and CLDN23 are associated with the clinical value in colorectal tumors." (PMID 37799140, 2023). "According to the level of CLDN2 protein by IHC analysis, 53/104 colorectal tumour tissues positively expressed CLDN2, significantly higher than 9/85 CLDN2‐positive in adjacent normal tissues." (PMID 34965023, 2021).
E. coli infection (3 papers, 2014 to 2020). "Immunofluorescence microscopy revealed a redistribution of the tight junction proteins occludin and claudin-3 and increased expression of claudin-2 upon E. coli infection." (PMID 24637645, 2014). "Six genes (CLDN20, PARD6B, CD151, CDH11, CLDN2 and F11R) related to the GO biological process “Cell junction organization” were upregulated by E. coli infection, whereas these genes were not induced by EPS." (PMID 32234079, 2020).
endometriosis (3 papers, 2020 to 2022). The growth of functional endometrial tissue in anatomic sites outside the uterine body. "In EEC tissues, CLDN-2 is overexpressed together with malignancy, while in endometriosis tissues a change in the localization of CLDN-2 is observed." (PMID 34944960, 2021). "In EEC tissues, angulin-1/LSR and ASPP2 are reduced and CLDN-2 is overexpressed together with malignancy, while in endometriosis tissues a change in the localization of angulin-1/LSR and CLDN-2 is observed." (PMID 34944960, 2021). "In EEC tissues, angulin-1/LSR and ASPP2 are reduced and claudin-2 is overexpressed during malignancy, while in the tissues of endometriosis changes in localization of angulin-1/LSR and claudin-2 are seen." (PMID 34944960, 2021). "Additionally, for claudin-2, a cytoplasmic shift in endometrioid endometrial carcinoma was reported, as was also the case for claudin-11 in endometriosis." (PMID 36428908, 2022). "Accordingly, angulin-1/LSR, ASPP2 and CLDN-2 may be as biomarkers for diagnosis or targets for treatment of endometriosis and EEC." (PMID 34944960, 2021). "Positivity for claudin-2 was further identified in the majority of endometriotic epithelial cells and lesions irrespective of the three endometriotic entities: ovarian, peritoneal or deep-infiltrating endometriosis." (PMID 32140805, 2020). "Thus, in this study, we examined claudin-2 and claudin-3 expression in eutopic and ectopic endometrium to further clarify the role of cell-to-cell contacts in endometriosis." (PMID 32140805, 2020). "From our results, we conclude that localization of claudin-2 and claudin-3 is highly stable in eutopic and ectopic endometrium without any loss of the epithelial phenotype and thus do not contribute to the pathogenesis of endometriosis." (PMID 32140805, 2020). "A detailed quantification with HSCORE was performed for claudin-2 and claudin-3 in endometrium without endometriosis and in cases with endometriosis compared to the three endometriotic entities: peritoneal, ovarian, and deep-infiltrating endometriosis." (PMID 32140805, 2020).
gastric neoplasm (3 papers, 2013 to 2023). A benign or malignant neoplasm involving the stomach. "The expression of Ki67 and NOS2 was independently associated with CLDN2 in non-cancerous adjacent tissue, explaining 83% in its variation, and BCLxL was independently associated with CLDN2 in gastric tumors, explaining 64% in its variability." (PMID 32630408, 2020). "As compared to EC, in which expression of 12 genes was altered, gastric tumors had significantly upregulated expression of only two (Ki67 and CLDN2) and downregulated one (BCL2)." (PMID 32630408, 2020).
nephrocalcinosis (3 papers, 2024 to 2025). Nephrocalcinosis is a disorder that occurs when too much calcium is deposited in the kidneys. "The authors identified a corticomedullary calcium gradient that was highest in papilla and exacerbated in tubule-specific Cldn2-KO mice, providing a mechanistic explanation for the development of nephrocalcinosis and support for the vas washdown hypothesis." (PMID 41321305, 2025). "The finding that kidney-specific Cldn2-KO mice developed papillary nephrocalcinosis despite normocalciuria suggests that their normal urine calcium might be masking an accumulation of calcium within the medullary tissue." (PMID 41066193, 2025). "The discovery that kidney tubule–specific Cldn2-KO mice developed nephrocalcinosis despite normocalciuria led Behm and colleagues to test whether the interstitial calcium gradient was increasing in these mice." (PMID 41321305, 2025). "The injury caused by nephrocalcinosis cannot explain the complex phenotype of Trpv5 Atp6v1b1 dKOs, especially since other mouse models with nephrocalcinosis (Cldn2 KO and Cldn10 ksp cKO) do not develop this severe pathology." (PMID 38339056, 2024).
peritonitis (3 papers, 2013 to 2022). Inflammation of the peritoneum (tissue that lines the abdominal wall and covers most of the organs in the abdomen). "The expression of Claudin-2, a channel protein associated with tight junctions, is highly up-regulated during peritonitis, and due to its association with epithelial permeability, it has been postulated to promote inflammation." (PMID 25946026, 2015). "Peritonitis induced a threefold increase in intestinal permeability, which is associated with increased claudin-2 expression and a change in subcellular localization." (PMID 23505542, 2013). "The finding that the elevated expression of Claudin-2 in peritonitis was corrected reflects the important role of IAP in treating early stages of peritonitis." (PMID 25946026, 2015). "In a study, IAP supplementation was found to reduce intestinal permeability and suppress gut bacterial translocation in the blood stream, liver, and lung in a mouse model of peritonitis, and also enhance transepithelial resistance and decrease claudin-2 expression in Caco-2 cells." (PMID 35694541, 2022).
prostate carcinoma (3 papers, 2013 to 2024). A carcinoma that arises from epithelial cells of the prostate gland. "For example, claudin-3 and claudin-4 were expressed at high levels in endometrioid adenocarcinoma and prostate cancer; claudin-10 expression was up-regulated in hepatocellular carcinoma and thyroid papilloma; claudin-2 has been reported to be up-regulated in thyroid cancer and endometrial cancer." (PMID 24245968, 2013). "Additionally, CAPE is effective in combating MDR in lung and prostate cancer by downregulating the synthesis of claudin-2, suppressing the NF-κB pathway, diminishing cytoplasmic reserves of GSH (reduced glutathione), and decreasing apoptotic regulators (cIAP1, cIAP-2, and XIAP)." (PMID 39125822, 2024).
triple-negative breast carcinoma (3 papers, 2015 to 2023). An invasive breast carcinoma which is negative for expression of estrogen receptor (ER), progesterone receptor (PR), and human epidermal growth factor receptor 2 (HER2). "We previously demonstrated that Claudin-2 expression in murine triple-negative breast cancer cells promotes the formation of liver metastases." (PMID 25823815, 2015). "Intriguingly, decreased Lyn levels significantly reduced Claudin-2 expression in human and mouse triple-negative breast cancer cells." (PMID 25823815, 2015). "Furthermore, we analyzed the correlation between KK-LC-1 and CLDN2 in triple-negative breast cancer specimens." (PMID 36895039, 2023). "Thus, it is conceivable that CLDN2 expression in triple-negative breast cancer cells is controlled by an AP-1 complex composed of c-Fos and another Jun family member, such as Jun B or JunD." (PMID 25823815, 2015).
acute kidney injury (2 papers, 2017 to 2021). Sudden and sustained deterioration of the kidney function characterized by decreased glomerular filtration rate, increased serum creatinine or oliguria. "In addition, NKILA can enhance autophagy of HK2 cells through Mir-140-5p/CLDN2/LPS pathway to induce acute kidney injury." (PMID 34692467, 2021).
adenoma (2 papers, 2020 to 2024). A neoplasm arising from the epithelium. "In adenomas, 27.1% (n = 13) were found to have high CLDN2 expression, while the remaining 76.9% had low expression." (PMID 38540693, 2024).
Anxiety (2 papers, 2022 to 2024). Intense feelings of nervousness, tension, or panic often arise in response to interpersonal stresses. "Notably, gastrointestinal vagal deafferentation affected genes previously associated with anxiety modulation in the mouse amygdala (Cldn2, Mfrp, Ttr, F5, Clic6), although in opposite direction compared with acute or early-life stressors." (PMID 35965105, 2022).
Azoospermia (2 papers, 2021 to 2022). Absence of any measurable level of sperm,whereby spermatozoa cannot be observed even after centrifugation of the semen pellet. "Recently, a missense mutation in Cldn2 associated with obstructive azoospermia in a four-generation spanning family has been identified." (PMID 36523561, 2022). "Recently, a CLDN2 missense variant was described in a family with several male relatives affected by obstructive azoospermia." (PMID 31875237, 2021). "It remains to be shown whether CLDN2 variants can be responsible for obstructive azoospermia, e.g., by influencing the paracellular water transport in the epididymis." (PMID 31875237, 2021).
COVID-19 (2 papers, 2020 to 2024). A disease caused by infection with severe acute respiratory syndrome coronavirus 2. "When the cells were treated with MVs derived from R patients vaccinated with the COVID-19 vaccine, the response of the cells was changed, and a significant reduction in the expression of OCLN, CLDN2, and E-CAD (p < 0.005) was induced, while the other proteins were not significantly modulated." (PMID 39201543, 2024).